MGAT4A (alpha-1,3-mannosyl-glycoprotein 4-beta-N-acetylglucosaminyltransferase A)
Description:
Glycosyltransferase that catalyze the transfer of GlcNAc from UDP-GlcNAc to the GlcNAcbeta1-2Manalpha1-3 arm of the core structure of N-linked glycans through a beta1-4 linkage and participates in the production of tri- and tetra-antennary N-linked sugar chains. Involved in glucose transport by mediating SLC2A2/GLUT2 glycosylation, thereby controlling cell-surface expression of SLC2A2 in pancreatic beta cells (By similarity).
Synonyms: GnT-IVa; GnT-4a; GNT-IV
Tractability: Antibody: UniProt places it where antibodies can reach, with medium confidence; UniProt predicts a signal peptide or a membrane-spanning region; its Gene Ontology location is reachable by antibodies, with medium confidence. PROTAC: ubiquitination databases record sites on it.
Gene: Protein-coding gene on chromosome 2 (98,619,106 to 98,732,639, reverse strand). Ensembl gene ENSG00000071073.
Subcellular location: Golgi apparatus membrane (Alpha-1,3-mannosyl-glycoprotein 4-beta-N- acetylglucosaminyltransferase A); Secreted (Alpha-1,3-mannosyl-glycoprotein 4-beta-N- acetylglucosaminyltransferase A soluble form)
Subcellular location (Human Protein Atlas): Golgi apparatus; Predicted to be secreted
Pathways (Reactome):
Metabolism of proteins: N-Glycan antennae elongation; Post-translational protein phosphorylation; Regulation of Insulin-like Growth Factor (IGF) transport and uptake by Insulin-like Growth Factor Binding Proteins (IGFBPs)
Disease: Maturation of spike protein
Gene Ontology:
Molecular function: alpha-1,3-mannosylglycoprotein 4-beta-N-acetylglucosaminyltransferase activity; acetylglucosaminyltransferase activity; alanine-glyoxylate transaminase activity; protein homodimerization activity; glycosyltransferase activity
Biological process: glycoprotein biosynthetic process; glyoxylate metabolic process; N-glycan processing; protein N-linked glycosylation; viral protein processing
Cellular component: extracellular exosome; endoplasmic reticulum; endoplasmic reticulum lumen; endoplasmic reticulum-Golgi intermediate compartment; extracellular region; Golgi membrane; Golgi stack; peroxisome
Genetic constraint (gnomAD): Loss-of-function variants: 16 observed, 32.72 expected, observed/expected ratio (o/e) 0.49, 90% interval 0.33 to 0.74. The upper end of that interval is the gene's LOEUF score, 0.74, which puts it in group 3 of 6, group 1 being the genes least tolerant of losing a copy. Missense variants: 331 observed, 413.56 expected, observed/expected ratio (o/e) 0.8, 90% interval 0.73 to 0.88. Synonymous variants: 142 observed, 141.91 expected, observed/expected ratio (o/e) 1, 90% interval 0.87 to 1.15.
Homologues: Orthologues: chimpanzee MGAT4A (100% identical), macaque MGAT4A (99% identical), rabbit MGAT4A (97% identical), dog MGAT4A (96% identical), guinea pig MGAT4A (96% identical), pig MGAT4A (96% identical), rat Mgat4a (95% identical), mouse Mgat4a (94% identical), tropical clawed frog mgat4a (76% identical), zebrafish mgat4a (75% identical), Drosophila melanogaster Mgat4a (41% identical), Drosophila melanogaster Mgat4b (26% identical). Paralogues in human: MGAT4B (62% identical), MGAT4C (27% identical), MGAT4D (26% identical).
Diseases named in the same sentence as MGAT4A in open-access papers:
MGAT4A is named in the same sentence as 26 diseases in open-access papers, as found by Europe PMC text mining. Sharing a sentence is not in itself a finding about the gene and the disease. The quoted sentences say what the papers report.
diabetes (5 papers, 2007 to 2024). "Furthermore, the mRNA levels of human MGAT4A were also shown to be reduced in pancreatic beta cells from diabetes patients." (PMID 35854001, 2022). "However, our qPCR data show that there is an increase of Mgat4a in diabetes, which could, together with other Mgat enzymes, promote UT-A1 glycan branching." (PMID 26483702, 2015). "The role of MgaT4a on controlling the traffic of GLUT2 in pancreatic β cells was described in these mice, linking a high fat diet with the development of experimental diabetes in mice." (PMID 17953760, 2007). "Moreover, uptake of a high-fat diet in mice reduced expression of the Mgat4a gene, and human diabetes patients also exhibited lower expression of MGAT4A mRNA, further demonstrating the involvement of GnT-IVa in the development of type 2 diabetes." (PMID 38879010, 2024).
schizophrenia (5 papers, 2017 to 2022). A major psychotic disorder characterized by abnormalities in the perception or expression of reality. "And the other 4 genes have been associated with schizophrenia (MGAT4A), Leigh syndrome (ADI1, OMIM: 256,000), congenital hypomyelinating neuropathy (PLEKHA1, OMIM: 605,253), and ID (PCK2), respectively." (PMID 36320054, 2022). "Low expression of MGAT4A in the dorsolateral prefrontal cortex was reported in cases of schizophrenia." (PMID 36061196, 2022). "There is some evidence for association of LOC105369506 to childhood antisocial behavior, while MGAT4A shows links to schizophrenia." (PMID 36310845, 2022). "MGAT4A, a schizophrenia-relevant gene, is involved in the GO:0,006,487, GO:0,043,234, and ko01100 pathways." (PMID 36320054, 2022). "Recently, protein levels of important glycosylation enzymes, B3GNT8 and MGAT4A, were found decreased in the prefrontal cortex in schizophrenia (12 case–control pairs), whereas in our study B3GNT1, B3GNT3 and MGAT1 transcripts were downregulated in schizophrenia cases." (PMID 28418402, 2017).
hyperglycaemia (4 papers, 2007 to 2024). "The distinct effects of the two enzymes are also demonstrated in MGAT4A KO mice presenting with hyperglycemia due to selective N-glycan branching of the GLUT2 transporter by MGAT4A, despite the co-expression of MGAT4B in the pancreas." (PMID 37919266, 2023). "However a more interesting plausible explanation is the higher level of MGAT4A gene expression exhibited by the T2D subjects, is a consequence of a low pro-inflammatory state derived of chronic hyperglycaemia, a common condition in T2D patients." (PMID 17953760, 2007).
pancreatic cancer (3 papers, 2016 to 2025). "MGAT3 gene is also regulated by DNA methylation in other types of cancer and also during the process of EMT; in addition, GnT-IV genes (MGAT4A and 4B) were reported to be regulated by DNA methylation in pancreatic cancer." (PMID 27136596, 2016). "Similarly, aberrant overexpression of GnT-IV (MGAT4A and MGAT4B) has been reported in pancreatic cancer." (PMID 41461315, 2025).
breast carcinoma (2 papers, 2022 to 2024). "The protective effect of MGAT4A has been observed in breast cancer, in which diminished expression is related to drug resistance." (PMID 38278930, 2024). "In breast cancer, MGAT1, MGAT2 and MGAT3 were downregulated, but MGAT4A, MGAT4B, and MGAT5 were increased." (PMID 36185271, 2022).
brain tumor (1 paper, 2026). "Silencing MGAT4A inhibits GSC invasion and tumorigenic capacities, including self-renewal and proliferation, both in vitro and in an orthotopic brain tumor xenograft model." (PMID 41810076, 2026).
hepatic cancers (1 paper, 2020). "For instances, MGAT1, MGAT4A, and GXYLT2 are unfavorable prognostic markers, while MAN1C1, GCNT4, and STT3B are favorable markers in non-hepatic cancers." (PMID 32850363, 2020).
pulmonary sarcoidosis (1 paper, 2014). Sarcoidosis affecting the lung parenchyma. "In a gene expression study of pulmonary sarcoidosis tissues and healthy lung specimens, MGAT4A was up-regulated 1.66-fold (p = 0.0145, uncorrected for multiple testing) in sarcoidosis tissue." (PMID 24663488, 2014).
cancer (7 papers, 2015 to 2025). A tumor composed of atypical neoplastic, often pleomorphic cells that invade other tissues. "Given the association of MGAT4A with aggressive EC, we investigated its role in cancer progression." (PMID 39527463, 2024). "The dysregulation of MGAT4A in various cancer types suggests that identification of MGAT4A's substrates may account for its tumor‐promoting role." (PMID 39527463, 2024). "We also measured the protein levels of three glycosyltransferases (MGAT3, MGAT4a, and MGAT5) previously reported to correlate with CD147 glycosylation in clinical samples such as cancer tissues." (PMID 35050217, 2021). "Notably, we previously showed that top genes of this program (LDHB, GSTK1, DGKA, APRT, MGAT4A, and NMRK1) are predictive of the response of patients with cancer to ICIs." (PMID 40187353, 2025). "We observed a significant overexpression of Mgat5 glycogene as well as Mgat4a and Mgat3 in LGD, HGD, and carcinoma, when compared with inflamed tissue, suggesting an overall increase in complex N-glycosylation pathway along CAC development, which is in accordance with our human results." (PMID 40087977, 2025).
tumor (4 papers, 2014 to 2024). "Furthermore, in our own cohort containing 60 EC specimens, high MGAT4A protein expression by immunohistochemistry (IHC) assay was significantly associated with advanced tumor stage, grade, histology status, ER/PR‐negative status, as well as myometrial invasion." (PMID 39527463, 2024). "3‐miRNA expression signature score showed a significant inverse correlation with MGAT4A expression (r = −0.3354, p < 0.001), advanced tumor stage (p < 0.05) and good clinical outcome (p = 0.0004) in TCGA‐UCEC cohort." (PMID 39527463, 2024). "LGALS1, B4GALT6, and GALNT11 were upregulated and MGAT5, MAN1A1, MANBA, LUM, GALNT1 and 7, HAPLN3, and ST6GALNAC5 were downregulated in Fra-2 cl 1 select primary tumours, while MGAT4A was upregulated." (PMID 34693476, 2022). "Further evaluating the microarray data of the scid and the select group, we observed that many genes which are crucial for glycosylation show an altered expression: for example, MAN1A1, MAN2A1, and GALNT 5 and 7 were downregulated in Fra-2 cl 1 scid primary tumours, whereas MGAT4A was upregulated." (PMID 34693476, 2022). "We observed a substantial increase in glucose uptake (p < 0.05) and tumor growth (p < 0.001) in Ishikawa xenografts with ectopic expression of GAL9; while MGAT4A inhibition reversed these effects (p < 0.05)." (PMID 39527463, 2024). "This molecular EC subtype relied on MGAT4A/GAL9‐mediated GLUT1 protein modification, promoting glucose metabolism for tumor proliferation and invasion." (PMID 39527463, 2024). "The overexpressed MGAT4A with GAL9 collaboration further increased the N‐glycan modification and membrane localization of GLUT1 to promote glycolysis for tumor proliferation and invasion." (PMID 39527463, 2024).
metabolic disorder (1 paper, 2007). "Interestingly the WBC count was higher in the T2D subjects compared to the healthy individuals, suggesting that the increase in MGAT4A transcripts levels and WBC count are related with the metabolic disorder observed in T2D patients." (PMID 17953760, 2007).
MGAT4A also shares sentences with these, for which no sentence is quoted: type 2 diabetes (3 papers); choriocarcinoma (2); hepatocellular carcinoma (2); cardiovascular diseases (1); colorectal tumors (1); congenital hypomyelinating neuropathy (1); endometrial carcinoma (1); glioblastoma (1); Impaired glucose tolerance (1); infection (1); Leigh syndrome (1); leukemia (1); lung diseases (1); oropharyngeal squamous cell carcinoma (1); sarcoidosis (1).